CD4 (CD4 molecule)
Diseases named in the same sentence as CD4 in open-access papers (continued):
Sharing a sentence is not in itself a finding about the gene and the disease.
COVID-19 (continued). "We found plasma cells and memory B cells to be significantly increased in COVID-19 patients and naive B cells, resting memory CD4 T cells, resting natural killer (NK) cells, and Eosinophils significantly decreased in COVID-19 patients." (PMID 34200572, 2021). "More patients aged≥60 years were classified as severe or critical type of COVID-19 (p=0.001), and had lower baseline CD4 and CD8 counts (p<0.001), compared with those aged 60 years." (PMID 34149679, 2021). "At the single-cell RNA-seq level, the increased CD4+/CD8+ T-cell ratio was confirmed when comparing COVID-19 patients to healthy controls." (PMID 34226537, 2021). "In particular, caspase-1 expression is distinct in CD4+ T lymphocytes in hospitalized patients with COVID-19." (PMID 34360684, 2021). "Pre-trained T cell immunity is likely generated by previous exposure to eHCoVs and is generally thought to promote viral clearance; however, dysregulated CD4 T cell responses have also been shown to contribute to cytokine storm in severe COVID-19 patients." (PMID 33430856, 2021). "The CD4+ cells showed impaired function as well as alleviated IFN-γ secretion in severe COVID-19 patients with higher age and comorbidity index." (PMID 34276652, 2021). "The critical role of the Th17 subset of CD4+ T cells, possibly IL-6-induced, in COVID-19 immunopathology and vaccine-induced immune enhancement was highlighted by recent studies." (PMID 35004790, 2021). "Immune response and CD8+ T cell infiltration were involved in the COVID-19 pathological process, and reduction of CD4+ T cells, CD8+ T cells, and NK cells was observed on day 7 after corticosteroid use." (PMID 34122093, 2021). "We found that the proportion of H3K27Me3+VDAC1+ CD4 T cells was highly predictive when comparing healthy controls with COVID-19 patients." (PMID 33691089, 2021). "Post COVID-19 Ab+ had significantly higher activated CD4+ T cells in response to SARS-CoV-2 S C-terminal peptide pool compared to HC (p = 0.005)." (PMID 34322120, 2021). "The results confirmed that decreased CD4+T cell level and CD8+T cell level were associated with poor prognosis in COVID-19 patients." (PMID 33435865, 2021). "Second, hyperglycemia in severe COVID-19 patients has been demonstrated to down-7regulate the proportion of immune cells, including CD4+, CD8+ T cells and macrophages." (PMID 33480978, 2021). "An insignificant effect of SARS-CoV-2 variants on both CD4+ and CD8+ T-cell responses in COVID-19 convalescents and recipients of COVID-19 mRNA vaccines." (PMID 34696303, 2021). "In the past year, multiple studies were conducted to evaluate the role of CD4 T cell subsets in the pathogenesis of COVID-19." (PMID 34578138, 2021). "In conclusion, we confirmed that SARS-CoV-2 S protein induces strong and broad CD4+ T cell responses in the majority of COVID-19 convalescent patients." (PMID 34805136, 2021). "The pan-caspase inhibitor emricasan inhibited the caspase-1 activity of CD4+ T lymphocytes in the blood of patients with moderate to severe COVID-19." (PMID 34360684, 2021). "SARS-CoV-2 Spike (S) protein reactive T cells were identified in immunocompetent patients suffering from moderate, severe, and critical COVID-19 and a dominance of CD4+ T-cell over CD8+ T-cell response was observed in severe COVID-19 patients." (PMID 34835067, 2021). "We observed no significant change of GPR15 expression in patients with active or after COVID-19 on CD4+ memory T cells." (PMID 33959123, 2021). "A London HIV clinic found that 18 PLWH who were hospitalized with COVID-19 had a lower median CD4+ T-cell count (395 vs. 573 cells/μl, P = 0.03) compared with their 2699 PLWH outpatients." (PMID 33587448, 2021). "The immune response in severe cases of COVID-19 commonly showed lymphopenia with low numbers of multiple cell types including CD4+ and CD8+ T cells." (PMID 35128530, 2021).
COVID-19 (continued). "Severe COVID-19 patients have a reduced frequency of multi-functional CD4+ T cells (producers of at least two types of cytokines) and apparently, this functional damage predisposes to severe disease." (PMID 33596401, 2021). "There was a minimal presence of Spike-specific CD4+ T cells in unexposed donors with a remarkably high magnitude in case of recovery from mild COVID-19." (PMID 33777028, 2021). "Anti–spike protein receptor binding domain antibody responses in patients who have recovered from COVID-19 correlated with the magnitude of spike protein–specific CD4+ T cell responses." (PMID 34591596, 2021). "Spike-specific memory CD4+ T cell frequencies at 7 months were similar to those observed for COVID-19 cases (COVID-19 samples collected 170 to 195 days PSO)." (PMID 34519540, 2021). "Further, post COVID-19 Ab+ had significantly higher HCoV-229E S N-term reactive CD4+ T cells (p = 0.05)." (PMID 34322120, 2021). "Vaccine-generated spike-specific memory CD4+ T cells 6 months after the second dose of the vaccine were comparable in quantity and quality to COVID-19 cases, including the presence of T follicular helper cells and interferon-γ–expressing cells." (PMID 34519540, 2021). "SARS-CoV-2-specific T cell responses have been detected in almost all COVID-19 patients, with more prominent CD4+ T cell responses compared to CD8+ T cell responses." (PMID 34696342, 2021). "Immune response pathways in COVID-19 have recently been reviewed, showing a relevant role of CD4 + and CD8 + T cells by targeting different targets of SARS-CoV-2 to contrast the infection while persisting in the resolution phase of the disease." (PMID 33765288, 2021). "The lymphocyte analysis studies among patients with COVID-19 demonstrate that T lymphopenia—in particular, a decrease in CD4+ T cells—were common among patients with COVID-19, and more evident in severe cases." (PMID 33952300, 2021). "Asymptomatic COVID-19 patients have been shown to have lower levels of anti-SARS-CoV-2-specific CD4+T cell responses and specific IgA, IgG and IgM antibodies against SARS-CoV-2." (PMID 33922198, 2021). "Our results are in contrast with the data obtained from peripheral blood samples of COVID-19 patients, as this shows decreases in total lymphocytes, CD4+ T-cell, CD8+ T-cell, B-cell, and NK cell counts." (PMID 34899680, 2021). "Recovered COVID-19 patients have an increased number of antibody-secreting cells and activated CD4+ and CD8+ T cells." (PMID 34075347, 2021). "The presence of the specific CD4+ T-cells in COVID-19 patients has been shown to be decisive for the induction of potent B-cell responses." (PMID 34830421, 2021). "Even though the role of SARS-CoV-2–specific T cell responses in COVID-19 is still unclear, virus-specific CD4+ T cells can provide help for B cell activation and maturation and Ab induction." (PMID 33908897, 2021). "Corroborating our previous observations, the fraction as well as the absolute number of CD3+CD4+CD45RO+ T cells staining positive for vedolizumab was markedly reduced in patients with COVID-19." (PMID 33959123, 2021). "This distinguishes COVID-19 from other viral respiratory infections and bacterial sepsis, where lymphocytopenia is evident but CD4+/CD8+ ratios are decreased." (PMID 34226537, 2021). "CD4 Th1 cells should vigorously activate virus antigen-experienced B cells that should already pre-exist in most COVID-19-patients." (PMID 33923363, 2021). "We observed clonal expansion and characterized the activation profile of tissue-resident memory-like CD4+ T cells in the lungs of patients with COVID-19 that persist even after clearance of the virus." (PMID 33622974, 2021). "CD4+ T-cells in the COVID-19 group also had higher expression levels of the activation markers OX40 and CD69, as well as the chemokine receptors CCR6 and CCR4, than the other respiratory infection group, implying a stronger activation." (PMID 34835045, 2021).
COVID-19 (continued). "Platelets and CD4+ T lymphocyte count were lower in the acute COVID-19 group than in the post-COVID and the control groups." (PMID 34635073, 2021). "Based on these observations, immunomodulatory approaches for stimulating adaptive immunity, particularly CD4 T cells, through IL-10 blockade, have potential as a therapeutic approach for patients with COVID-19." (PMID 34251989, 2021). "Even when relating the expression of α4β7 on CD45RO+ memory T cells to total CD3+CD4+ T cells, frequencies were decreased in COVID-19 patients compared to healthy controls." (PMID 33959123, 2021). "Decreased CD4 protein expression on total peripheral monocytes in people with COVID-19 correlates with disease severity as measured by flow cytometry." (PMID 34108966, 2021). "We observed a remarkably higher frequency of Spike-specific memory CD4+ T cells in recovered patients than the unexposed donors (Unexposed vs COVID-19, P<0.0001)." (PMID 33777028, 2021). "Next, we measured the stimulation index of antigen specific stimulations over the unstimulated DMSO control to quantify CD4+ T cell reactivity in case of pre-existing immunity and in long-term post recovery from COVID-19." (PMID 33777028, 2021). "Because the mild COVID-19 patients showed robust Spike-specific CD4+ T cells reactivity, we examined if a similar finding would extend to SARS-CoV-2 B cell responses." (PMID 33777028, 2021). "CD16+CD56+%, CD4+/CD8+ratio, CD19+, and CD3+CD4+ were identified as predictors of COVID-19 diagnosis by logistic regression." (PMID 34150910, 2021). "As a result, the CD4:CD8 ratios were significantly higher in severe patients than in the healthy donors (6.7 ± 1.3 in COVID-19 vs. 2.5 ± 0.3 in HD, P=0.0226)." (PMID 33603759, 2021). "In COVID-19–recovered donors, S-specific CD4+ T cells were already detected in the convalescent phase, which were boosted after the first vaccination." (PMID 34035118, 2021). "Particularly, we observed an expansion of CD8+ and CD4+ T cells, NK cells, HLA-DRhigh and HLA-DRlow monocytes in COVID-19 patients at diagnosis compared to post-COVID and healthy blood donors." (PMID 34944610, 2021). "Virus-specific memory CD4 T cells, a feature of cellular immunity, were also detected in >90% of COVID-19 cases between six and eight months after infection." (PMID 34945178, 2021). "A recent study has reported a relative loss of peripheral blood CD45RA+CD27+CCR7+CD95− naïve CD4 T cells compared with the controls, but increased CD45RA−CD27−CCR7+ EM2 and CD45RA+CD27−CCR7− EMRA cells in patients with COVID-19 compared to the healthy donors." (PMID 34696395, 2021). "Our group previously reported that the CD3+T cells were the major cell types that were suppressed in patients with COVID-19, and the reduced CD4+ and CD8+ T cell counts were predictive of disease progression." (PMID 33717140, 2021). "The 395 COVID-19 patients were divided into two groups according to the lower limit of laboratory CD4+T cell level reference value: the lower CD4+T cell level group and the higher CD4+T cell level group." (PMID 33435865, 2021). "The cluster analysis also showed a higher CD8+/CD4+ ratio among AIM+ T cells in the COVID-19-recovered older group." (PMID 34868051, 2021). "After spike stimulation, a significant elevation for central and effector memory CD4+ T-cells frequencies was detected for COVID-19, followed by all memory subsets for CD8+ T cells, except for naive subset, compared to the unexposed group." (PMID 34571855, 2021). "We observed reduced expression of CD4 in all severity types of COVID-19 patients compared to HLTY and INFL patients; in contrast, CD8 was under-expressed solely among TUBE early patients compared to HTLY, with levels similar to those of INFL patients." (PMID 34135895, 2021). "Conversely, COVID-19 death is associated with reduced T cells, with lymphocyte subset analyses implicating deficiency in both CD3+CD4+ and CD3+CD8+ cells." (PMID 33547083, 2021).
COVID-19 (continued). "Presence of SARS-CoV-2 responsive CD4+ T cells is definitely protective, as found in convalescent COVID-19 patients." (PMID 34680460, 2021). "Nevertheless, the proportion of subjects with verified infection that developed CD4+ T-cell responses is in line with previous studies showing that most COVID-19 patients develop such responses." (PMID 34795668, 2021). "While only one study reported that CD4+ T cell count was independently associated with ICU admission, several results highlighted the role of CD8+ T cells in COVID-19." (PMID 35965490, 2021). "In fact, the sample size was sufficient to determine the existence of cross-reactive CD4+ T cells and to reveal the persistence of memory CD4+ T cells in several months after recovery from COVID-19." (PMID 33777028, 2021). "In contrast, patients with COVID-19 had significantly more effector and central memory CD4+ T cells compared to RTx patients and healthy individuals and an equal frequency of naïve CD4+ T cells compared to RTx patients." (PMID 34228322, 2021). "Secondly, the lack of dynamic measurement for CD4+T and CD8+T cell levels in the patients included in this study made the evaluation of the relationship between CD4+T cell level and disease changes in COVID-19 patients incomplete." (PMID 33435865, 2021). "The median proportion of CD4+ cells was lower in critical COVID-19 than severe COVID-19 patients (respectively, 3.8 vs. 11.3, p < 0.05)." (PMID 34064802, 2021). "Both post COVID-19 groups had significantly higher dp TNFα+ IL-2+ SARS-CoV-2 S N-term reactive CD4+ T cells compared to HC (Ab−: p = 0.04; Ab+ p = 0.05)." (PMID 34322120, 2021). "Recovered COVID-19 patients have been shown to exhibit robust and broad memory CD4+ and CD8+ T cell responses." (PMID 35250966, 2021). "In human COVID-19 infections, SARS-CoV-2-specific CD4+ T cells and CD8+ T cells are associated with less COVID-19 disease severity during an ongoing SARS-CoV-2 infection." (PMID 33408181, 2021). "It important to note that associated with the cytokine storm in COVID-19 patients with severe illness is elevated neutrophil count and reduced T lymphocytes mainly CD8+, CD3+ and CD4+ T-cells." (PMID 34287285, 2021). "Shi analyzed the PBMCs from COVID-19 patients using single-cell mass cytometry (CyTOF) and found CD4+ T-cell depletion, plasma cell expansion, and the reduced antigen presentation capacity in those patients." (PMID 34867988, 2021). "The accumulation of interferon-γ (IFN-γ)–producing CD4+ T cells in the BAL of patients with COVID-19 has also recently been described." (PMID 33622974, 2021). "Another report noted that mild cases of COVID-19 had a greater proportion of CD8+ T cells than CD4+ T cells." (PMID 34917088, 2021). "Within the lymphoid compartment, mild-moderate COVID-19 patients had better correlation between CD4+/CD8+ T cells and some B-cell subsets, whereas in critical COVID-19 patients such correlations between these lymphocyte subpopulations became more fragmented." (PMID 34226537, 2021). "The main difference in post COVID-19 versus unexposed HC were observed in IFNγ+TNFα+IL-2+ tp activated CD4+ T cells." (PMID 34322120, 2021). "SARS-CoV-2–reactive CD4+ T cells were detected in 34.2% (13/38) of non–COVID-19 controls, whereas 83.2% (79/95) of COVID-19 patients exhibited a SARS-CoV-2–specific response." (PMID 33945513, 2021). "The rapid development of lymphopenia has also been observed in COVID-19 patients with adverse outcomes, whereby CD4 + T-cells were more severely reduced than CD8 + T-cells." (PMID 33785846, 2021). "Circulating SARS-CoV-2 memory CD4+ T cell responses were quite robust; 42% (24/57) of COVID-19 cases at 1 month PSO had > 1.0% SARS-CoV-2-specific CD4+ T cells." (PMID 33408181, 2021). "Recent evidence has demonstrated that in severe COVID-19 patients, lymphopenia is a common feature, with drastically reduced numbers of CD4+ T cells, CD8+ T cells, B cells and NK cells." (PMID 34521370, 2021).
COVID-19 (continued). "Among T lymphocyte subpopulations in patients with COVID-19, both CD4+ and CD8+ T cell counts decreased, and the reduction in CD4+ T cells was more pronounced." (PMID 34164371, 2021). "The recent study illustrated the majority of CD4+ and CD8+ T cells circulating in the peripheral blood of COVID-19 patients reduces significantly, besides its excessive activation evidenced a high ratio of CD4 (3.47%) and CD38 (39.4%) cells." (PMID 33526007, 2021). "Lymphopenia is a prominent characteristic of critically ill patients with COVID-19, resulting from the direct destruction of lymphocytes, especially CD4+ T and CD8+ T cells, or cytokine-mediated lymphocyte destruction." (PMID 33861750, 2021). "Our findings suggest that MILD COVID-19 patient-recovered exosomes are capable of favoring CD4+ T-cell activation by functioning as an antigen-presenting source and by promoting T-cell activation." (PMID 35111156, 2021). "We also found significantly higher proportions of effector CD8+ and CD4+ T cells in our COVID-19 convalescents, especially those with pre-existing cardiovascular risk, than healthy participants." (PMID 33752798, 2021). "On the other hand, we observed that cytotoxic (perforin containing) CD4 T cells are expanded in a subset of COVID-19 patients." (PMID 33777054, 2021). "HIV-1–mediated CD4+ T cell depletion associated with suboptimal T cell and humoral immune responses to SARS-CoV-2, and a decrease in the polyfunctional capacity of SARS-CoV-2–specific CD4+ T cells was observed in COVID-19 patients with active TB." (PMID 33945513, 2021). "For both of the two datasets, ssGSEA identified the increase of activated CD4 T cell, gamma delta T cell, type 2 T helper cell, activated dendritic cell, macrophage, and neutrophil (Wilcox test, p value < 0.05) in COVID-19 patients compared to healthy people." (PMID 34457122, 2021). "Given recent reports on lung infiltration by lymphocytes (CD4 T cells) in COVID-19 patients, we sought to investigate the prevalence of tissue CD4 and CD8 T cell populations in our cohort." (PMID 34441292, 2021). "We also found that SARS-CoV-2 S-specific reactive CD4+ T cells exhibited higher frequency than CD8+ T cells in recovered COVID-19 patients, with greater number of corresponding epitopes presented." (PMID 34805136, 2021). "The overall frequency of CD3+ and CD3+CD4+ T cells was similar in patients with active or previous COVID-19 and in controls." (PMID 33959123, 2021). "In HIV-infected patients with COVID-19, the proportion of an M. tuberculosis–specific CD4 response was significantly lower compared with that of SARS-CoV-2 (48% vs. 83%, respectively, P = 0.013)." (PMID 33945513, 2021). "Aberrant pathogenic CD4+ T-cells co-expressing IFN-γ and G-CFS have also been observed in severe COVID-19." (PMID 33584343, 2021). "Taken together, these results indicated that the SARS-CoV-2-specific CD4+ T cell responses induced by a single dose of inactivated COVID-19 vaccine were short-lived, but can be strengthened and perpetuated by the booster vaccination." (PMID 35003131, 2021). "Conversely, CD8 cytotoxic T cell responses, especially in effector memory and terminally differentiated effector CD8 cells, were diminished in COVID-19 patients with advanced age, while CD4 T cell responses were relatively normal." (PMID 34158111, 2021). "Naïve CD4+ T cell population was reduced 1.5-fold in patients with severe and critical disease, in comparison with mild COVID-19." (PMID 34122423, 2021). "The almost complete inhibition of cytokine release from activated T cells in ventilated COVID-19 patients strongly suggests that both CD4 + and CD8 + T cells are hyporeactive, as IL-3 and IFN-gamma are released from both, CD4 + and CD8 + T cells." (PMID 34021143, 2021). "In conclusion, our study provides a snapshot analysis of CD4+ T cells in the lungs of patients with severe COVID-19 and identifies TRM17 cells as one of the components of the lung-specific immune response." (PMID 33622974, 2021).